CXCL9 (C-X-C motif chemokine ligand 9)
Diseases named in the same sentence as CXCL9 in open-access papers (continued):
Sharing a sentence is not in itself a finding about the gene and the disease.
COVID-19 (129 papers, 2020 to 2025). A disease caused by infection with severe acute respiratory syndrome coronavirus 2. "In COVID-19 patients, high serum CXCL9 levels are associated with severe conditions such as acute respiratory distress syndrome (ARDS)." (PMID 40313944, 2025). "For the majority of these cytokines and chemokines, including those that are typically associated with MAS (IL-6, IL-18, IFN-γ, TNF-α, CXCL9) the increase was less pronounced in COVID-19 critical condition than in MAS patients." (PMID 34226537, 2021). "The consequences of these protein interactions need to be experimentally elucidated, however our results suggest that altered levels of TNF, IL-6 and CXCL9 in COPD patients may be involved in the initial steps that predispose COPD patients to severe COVID-19." (PMID 34335580, 2021). "Our study suggests that COPD patients have a systemic dysregulation in chemokine networks (including HGF and CXCL9) that could make them more susceptible to severe COVID-19." (PMID 34335580, 2021). "Furthermore, the patients who ultimately died of COVID-19 exhibited significantly elevated levels of chemokines associated with monocytes and T cell recruitments and survival, such as CXCL9 and CCL2110." (PMID 34188167, 2021). "In the context of viral infections, elevated levels of CXCL9 and CXCL10 have been linked to hyperinflammatory states and disease severity, particularly in respiratory infections such as influenza and COVID-19." (PMID 41425601, 2025). "Because cytokine and chemokine levels are relevant in the context of ARDS patients with COVID-19, serum levels of CXCL9 and CXCL10 during the acute phase were compared to both chemokines’ levels during recovery phases (4 months post-infection)." (PMID 41425601, 2025). "Some chemokines were also elevated in patients with severe COVID-19, as chemokine ligand (CCL)-2 (CCL2), CCL3, and chemokine CXC ligands (CXCL), CXCL8, CXCL9, CXCL10, and CXCL11 the most associated with this clinical condition." (PMID 39281667, 2024). "Patients with severe COVID-19 showed higher serum levels of CXCL9/MIG than those with mild to moderate disease." (PMID 39281667, 2024). "Strikingly, the four chemokines: Ccl2, Cxcl9, Cxcl10, and Cxl11, involved in the COVID-19 cytokine storm and found upregulated in both species in the present work, were also found to be overexpressed upon type I interferon application in vitro." (PMID 37350967, 2023). "The primary aim of this study was to investigate the association between mortality and the CXCL9, CXCL10, CXCL11, and CXCR3, chemokine levels, which contribute to the pathogenesis of COVID-19 through hyperinflammation, in patients with COVID-19." (PMID 37493737, 2023). "Evidence from clinical studies indicates that the severity of COVID-19 is positively associated with chemokine and inflammatory cytokine levels in the plasma of patients, such as TNF-α, IL-1β, IL-6, CCL2, CCL8, and CXCL9." (PMID 38104081, 2023). "Only two genes (RAC1, CXCL9) were upregulated in COVID-19(+) PU compared to the other two disease groups." (PMID 37026002, 2023). "In patients with chronic diseases, such as ILD and asthma, we found that CXCL9 levels were lower than those observed in samples from patients infected with COVID-19; however, some patients had CXCL9 levels exceeding the upper limit of the CXCL9 level in HCs." (PMID 37005469, 2023). "This study confirmed that CXCL9, CXCL10, CXCL11, and CXCR3 levels are associated with disease severity in patients with COVID-19." (PMID 37493737, 2023). "This study emphasizes the association between CXCL9, CXCL10, CXCL11, and CXCR3 levels and disease severity in patients with COVID-19." (PMID 37493737, 2023). "Patients with COVID-19 had elevated CXCL9 levels, which exceeded the threshold observed in HCs, even in mild cases, and were further elevated in severe cases." (PMID 37005469, 2023).
COVID-19 (continued). "Of note, Ccl8 and Ccl2 as well as Cxcl9 and Cxcl10, chemoattractants for monocytes and T cells, respectively, were significantly up-regulated in the lungs of AR-infected mice and in COVID-19 patients, in line with the increased recruitment of these cells." (PMID 34812647, 2022). "In this regard, it has been discussed that high production of some chemokines, such as CXCL8/IL-8, CCL-2/MCP-1, CCL3, CCL5, CXCL9, and CXCL10 are associated with lung damage and COVID-19 severity." (PMID 36685603, 2022). "MAS cytokine storms exhibited higher IL-6, IL-18, IFN-γ, TNF-α, and CXCL9 than severe COVID-19, with IFN-γ, IL-18, and CXCL9 being significantly lower in COVID-19." (PMID 35401519, 2022). "Higher expression of CXCL9 in COVID-19 patients than healthy controls and higher levels of CCL4 in severe COVID-19 patients were also found." (PMID 34760386, 2021). "In line with reduced IFN-γ, we found markedly lower levels of CXCL9 (an IFN-γ-induced chemokine) in COVID-19 critical patients compared to MAS, indicative of decreased type II interferon signalling." (PMID 34226537, 2021). "Of these age-correlated proteins, six had been also associated with COVID-19 severity: HGF and CXCL9 shown the highest coefficients while IL10RB, VEGFA, IL-6 and TNF showed low albeit significant correlation (r < 0.30)." (PMID 34335580, 2021). "Of note, IFN-γ and the IFN-γ–inducible chemokine CXCL9 were significantly increased in COVID-19 patients compared with HVs across severity groups." (PMID 33232303, 2021). "In our series, upregulation of IFN-γ and CXCL9 levels and increased whole-blood IFN-γ–associated transcriptional score were detected, indicating enhanced IFN-γ responses in COVID-19." (PMID 33232303, 2021). "Samples from COVID-19 positive individuals also displayed marked increases in CXCL9, CXCL10, and CXCL11 transcripts as well as transcripts in the AKT pathway." (PMID 34205098, 2021). "Additionally, we found that CXCL9 and CXCL11, chemokines both up regulated in bronchoalveolar lavage fluids from patients with COVID-19, increased during infection in all variants except Delta." (PMID 41157615, 2025). "This is a clear demonstration of productive SARS-CoV-2 infection of primary human macrophages and a direct association between natural infection of these cells and production of the pro-inflammatory cytokines characteristic of severe COVID-19 (CXCL9 and −10, IFNα, IL-6 and TNFα)." (PMID 39737903, 2024). "Our data suggest that therapeutic targeting of immune cell recruitment via the CXCL9– CXCL10–CXCL11/CXCR3 axis may be a valuable therapeutic strategy for resolution of inflammation in severe COVID-19, where it has become uncoupled from viral clearance." (PMID 36472908, 2023). "For the majority of these cytokines and chemokines, including those that are typically associated with macrophage activation syndrome (IL-6, IL-18, IFN-γ, TNF-α, CXCL9), the increase was less pronounced in COVID-19 critical condition than in macrophage activation syndrome patients." (PMID 35645351, 2022). "Changes in chemokine levels in peripheral blood of COVID-19 and influenza patients have been addressed by multiple studies, in particular CXCL9, CXCL10, CXCL11, CXCL16, CCL2, and CCL5 were altered in patients as compared to controls, and levels correlated to disease severity." (PMID 35371005, 2022). "Based on our results, we suggest that measuring levels of HGF, CXCL9, IL10-RB, MCP-3 and EN-RAGE could be further evaluated in larger cohorts as biomarkers of a “pre-morbid state” for the susceptibility to severe COVID-19." (PMID 34335580, 2021). "CXCL9 and CXCL10 are chemokines that have been widely implicated in pulmonary pathology, chronic obstructive pulmonary disease (COPD), other interstitial lung diseases (ILD), as well as pulmonary tuberculosis (TB) and also viral pneumonias, linked to COVID-19-associated ARDS." (PMID 41425601, 2025).
COVID-19 (continued). "These miRNAs target several pro-inflammatory cytokine and chemokine genes (e.g., TNF, CCL2, CXCL9, CXCL10, IL10, VEGFA) as well as cytokine and chemokine receptors and transduction factors (IL1R1, IL2RA, IFNAR2), reported as upregulated and associated with mortality in COVID-19 patients." (PMID 36032130, 2022). "For example, vitamin D could reduce ARDS (acute respiratory distress syndrome) in the context of COVID-19 by suppressing the expression of target genes, such as IL18, CXCL9 and CXCL10, that mediate the cytokine storm associated with the severe form of the disease." (PMID 35055093, 2022). "CXCL9 expression is upregulated in patients with interstitial lung disease (ILD), COVID-19, and asthma." (PMID 40313944, 2025). "Acute COVID-19 features an imbalanced host response marked by elevations of IL-1β, IL-6, IL-8, TNF-α and interferon-inducible chemokines (e.g., CXCL9/CXCL10) that govern myeloid recruitment, T-cell positioning, angiogenesis, and tissue remodeling." (PMID 41440526, 2025). "Four months after COVID-19, patients with prior ARDS and persistent pulmonary sequelae exhibit sustained elevations of anti-SARS-CoV-2 IgG and chemokines CXCL9 and CXCL10." (PMID 41425601, 2025). "Severe COVID-19 symptoms, such as ARDS or kidney failure, are also correlated with elevated CXCL9 levels." (PMID 40313944, 2025). "A significant increase in CXCL9 and CXCL10 chemokine levels was observed in samples from patients in the acute phase compared to the recovery phase of COVID-19." (PMID 41425601, 2025). "A key finding of this study is the significant correlation between serum levels of the chemokines CXCL9 and CXCL10 and anti-SARS-CoV-2 IgG titers in patients recovering from COVID-19." (PMID 41425601, 2025). "A comparative analysis of patients diagnosed with COVID-19, COVID-19 with concurrent maculopapular rash, or DRESS found that there were similar elevations of CXCL9, CXCL10, CXCL11, IFN-γ, IL-10, TNF-α, and IL-18 across the three groups." (PMID 39318634, 2024). "The persistence of high levels of IFN I and IFN III and proinflammatory cytokines, such as CXCL9, CXCL10, and IL-8, after COVID-19 recovery has been related to the development of LC." (PMID 38319477, 2024). "Regarding chemokines, the spike-specific IgG/IgM were associated positively with C-X-C motif ligand (CXCL) 5 but negatively with C-C motif ligand (CCL) 4, CXCL9, CXCL10, and CXCL11, which were reportedly upregulated in severe COVID-19." (PMID 38377029, 2024). "This classifier reinforced the prognostic importance of monocyte/macrophage, NK cell, and Th1-pathway activation, with prediction of severe COVID-19 driven by higher concentrations of IL-7, CXCL10, IL-15, and CXCL9, and lower concentrations of MDC and IL-5." (PMID 38368384, 2024). "High levels of these molecules, detected after macrophage treatment with VLPs (TNFα, IL-1β, CCL8, CXCL8, CXCL9, CXCL16, CXCL1, and CXCL2), were shown to correlate with severe COVID-19 in other studies." (PMID 38664730, 2024). "CXCL9, CXCL10, CXCL11, and CXCR3 levels were significantly higher in patients with severe COVID-19 group than in those with moderate disease." (PMID 37493737, 2023). "Together, these previously published observations and our targeted spatial analysis suggest the existence of a cellular circuit in which IFN-γ production by T and NK cells drives CXCL9/10/11 and BAFF production by myeloid cells in COVID-19." (PMID 36472908, 2023). "The levels of CXCL9, CXCL10, CXCL11, and CXCR3 were significantly higher in patients with COVID-19 than in healthy controls." (PMID 37493737, 2023). "In the ROC curve analysis of the ability of CXCL9, CXCL10, CXCL11, and CXCR3 to discriminate between moderate and severe COVID-19, the AUC values were 0.702, 0.939, 0.933, and 0.857, respectively." (PMID 37493737, 2023).
COVID-19 (continued). "Compared with the control group, there was extensive cytokine/chemokine correlations centered on IL-17A, IL-10, IL-6, CCL2, CXCL8, CXCL9 and CXCL10 and fewer correlations with IL-1β in the COVID-19 patients at baseline." (PMID 37662953, 2023). "This study examined the relationship between levels of the chemokines CXCL9, CXCL10, CXCL11, and CXCR3 and mortality in patients with COVID-19.." (PMID 37493737, 2023). "In genomic studies, some up-regulated homologous chemokines such as CXCL9, CXCL10 and CCL5, which are involved in the regulation of immune cell migration and activation in IPF, were also detected in COVID-19 patients." (PMID 37391786, 2023). "Serum CCL2, CCL3, CCL7, CXCL9, CXCL10, IL-1β and IL-1Ra levels increased in critical COVID-19 patients (n = 11) when compared to both severe COVID-19 patients (n = 25) and moderate COVID-19 patients (n = 14)." (PMID 36941580, 2023). "A small subset of genes involved in neutrophil and T cell activation (CXCL5, CXCL9, CCL21) were expressed in both COVID-19(+) TV and COVID-19(-) PU groups." (PMID 37026002, 2023). "We performed quantitative real-time PCR (qRT-PCR) for representative COVID-19 related host inflammatory cytokine genes and found that a cytokine panel (including IL-6, IL-1β, TNF-α, CCL2, and CXCL9) was induced by SARS-CoV-2 infection." (PMID 34979342, 2022). "They showed that IL-6, CCL2, CXCL8, CXCL9, and CXCL10/IP10 levels were higher in patients with MIS-C than in those with COVID-19." (PMID 35268506, 2022). "Repeating the analysis to only include first samples, showed again increased levels of CXCL9 and CCL20 in severe disease, but also increased levels of CXCL10 and a downregulation of CCL17 in patients with severe COVID-19." (PMID 34957382, 2022). "With regards to circulating chemokine levels, CCL3, CXCL9, CCL20, and CXCL1 were significantly upregulated in samples from individuals with severe COVID-19 when compared against mild and moderate cases." (PMID 34957382, 2022). "The disease is also associated with the elevated blood levels of other chemokines such as CCL2/MCP-1, CCL3/MIP-1α, CCL4/MIP-1β, CXCL9/MIG, CXCL10/IP-10 and CX3CL1/Fractalkine, which shows that CXCL1 is only one of many COVID-19 factors." (PMID 36613652, 2022). "In post-COVID-19 patients, we observed co-upregulation of groups of related red module proteins such as the CXCR3 chemokines (CXCL9, CXCL10, and CXCL11), and interleukin-1A (IL1A) and its antagonist IL1RN." (PMID 35151371, 2022). "A significant increase in CXCL2, CXCL8, CXCL9, and CXCL16 levels was reported in COVID-19 positive patients with generalized inflammation." (PMID 36016187, 2022). "Regarding the chemokines, COVID-19 patients showed gene expression levels of CXCL8 and CXCL9 similar to control subjects, but increased expression levels of CXCL10 and CXCL11 (by 290% and 150%, respectively)." (PMID 36009555, 2022). "Nevertheless, we found markedly lower levels of IFNG-induced chemokine CXCL10 in KD and CXCL9 and IL15 in both KD and severe COVID-19, suggesting blunted type II interferon signaling in both KD and severe COVID-19 conditions." (PMID 36159873, 2022). "Patients with fatal COVID-19 also showed significantly higher plasma levels of the neutrophil recruiting CXCL-8 as well as of the T and NK cell-attracting CXCL-9, as compared to severe and/or mild COVID-19 patients." (PMID 34473805, 2021). "In severe COVID-19 lung macrophages displayed high expression of IL-1β, IL-6, TNF-α and various chemokines (CCL2, CCL3, CCL4, CCL7, CXCL9, CXCL10 and CXCL11)." (PMID 34054832, 2021). "Levels of IL-6, IL-10, IL-15, IFN-γ, TNF-α, CCL2, CCL3, CCL4, CCL26, CXCL9 and CXCL10 were significantly elevated both in COVID-19 critical clinical condition and in MAS patients as compared to healthy controls." (PMID 34226537, 2021). "For COVID-19, CCL2 recruits neutrophils, monocytes, and macrophages, and CXCL9 and CXCL16 recruit T cells and NK cells to the site of viral infection." (PMID 35002688, 2021).
COVID-19 (continued). "When comparing COVID-19 mild vs critical patients, we identified IFNLR1, IFNA1, CXCL9, CXCL10, IL15 and IL15RA to be upregulated in mild patients." (PMID 33473155, 2021). "CXCR3, which mediates chemotaxis in response to IFN-induced inflammatory chemokines (CXCL9, CXCL10, CXCL11), was also upregulated in COVID-19 patients’ DC3, cDC2 and monocyte subsets but downregulated in cDC1, tDC, and pDC." (PMID 34614036, 2021). "An increase of HPG, CXCL9, CXCL10, IL-6, MCP-3, TNF and EN-RAGE has also been experimentally detected in patients with severe COVID-19." (PMID 34335580, 2021). "Importantly, chemokines and growth factors that are associated with COVID-19-induced cytokine storm and severe disease progression like CXCL9, CXCL10 (IP10), or VEGF-A exhibited particularly effective EPs 7630-mediated inhibition (CXCL9: 82% reduction; CXCL10: 80.9% reduction)." (PMID 34759825, 2021). "In particular, the cytokines IL-6, IL-8, CXCL9, and CXCL10 (IP-10) were identified as putative prognostic disease progression markers for COVID-19." (PMID 34759825, 2021). "Such a reaction, known as a cytokine storm, involves the release of potentially overwhelming amounts of pro-inflammatory cytokines and chemokines into the blood stream of COVID-19 patients including, but not limited to, IL-6, TNF-α, INF-γ, CXCL9 and CXCL10." (PMID 32958009, 2020). "The expression of several cytokines identified in the current study (i.e., IL1B, IL-6, TNF, CCL2, CXCL9, and CXCL10) were also seen in bronchoalveolar lavage (BAL) cells from COVID-19 patients, providing further support to our observation." (PMID 32882823, 2020). "ScRNA-seq analysis of BALF also revealed increased expression of CXCL9, CXCL10, CXCL11, and CXCL16 in all tested COVID-19 patients." (PMID 33335518, 2020). "Six chemokines (CXCL9, CXCL10, CCL4, CCL5, CCL27, and CXCL12) and eight interleukins (IL-1Ra, IL-2Ra, IL-3, IL-5, IL-9, IL-12p40, IL-15, and IL-16) were increased in both PLWH/COVID-19 and COVID-19-only." (PMID 41516165, 2025). "However, an IFNγ-induced signature is probably present in COVID-19, since CXCL10 (in common with CXCL9), an important IFNγ-induced chemokine, is highly detectable, as previously observed in several IFNγ-mediated syndromes." (PMID 39882243, 2024). "Moreover, cytokines MCP3/CCL7, MIG/CXCL9, IL1 beta, and SCF, key in viral infection immune responses, exhibited reduced levels in COVID-19 patients with sputum production during the acute phase in our study." (PMID 39052548, 2024). "Interestingly, IL-10, CXCL9, CCL3, and VEGF levels were significantly higher in the COVID-19 group than those in the HC group." (PMID 37422499, 2023). "Age corelated with CXCL9 (r = 0.409) and VEGFA (r = 0.312, all p < 0.05) significantly but did not correlate with any other inflammatory parameters or parameter related to oxidative stress in COVID-19 patients." (PMID 37832397, 2023). "We identified upregulation of several NFκB pathway components (NFKB2 and NFKBIA) and inflammatory cytokines (CXCL9, CCL17, and CCL21) in the presence of viral transcripts, in line with the abundant literature describing these molecules in the early steps of COVID-19 pathogenesis." (PMID 37858234, 2023). "Patients treated with ABA displayed, after two doses of COVID-19 mRNA vaccine, an impaired CD4 and CD4/CD8 T cell response with a reduced release of IFN-γ, as well as IFN-γ-inducible chemokines, such as CXCL9 and CXCL10, in response to peptides of the spike protein." (PMID 37316832, 2023). "Specifically, signatures of plasma cells (IGHG3, IGKC, IGHM, JCHAIN, IGHG2, IGKV4-1, IGLV3-1, IGHA1), activated fibroblasts (COL1A1, COL1A2, COL3A1), inflammatory cytokines (CXCL9, CCL18) and complement factors (C1QB, C1QC) dominated the DE genes for the COVID-19 lung sections." (PMID 37858234, 2023).